NOX5 (NADPH oxidase 5)
Diseases named in the same sentence as NOX5 in open-access papers (continued):
Sharing a sentence is not in itself a finding about the gene and the disease.
Hypertension (continued). "Although the exact role of Nox5 in the pathophysiology of human hypertension is unclear, findings show that mice expressing human Nox5 in the kidney and endothelium have elevated blood pressure, suggesting a potential role for Nox5 in blood pressure regulation." (PMID 30334629, 2019). "The Nox family consists of seven distinct isoforms: Nox1 through Nox5, as well as Duox1 and Duox2, each playing a unique role in regulating ROS production and contributing to various physiological and pathological processes, including hypertension and vascular dysfunction." (PMID 39974735, 2025). "Studies using a different promoter (Tie2) to drive NOX5 expression in endothelial cells found that NOX5 was linked to increased aneurysm formation in diabetic mice and hypertension in non-diabetic mice, but it did not result in a significant increase in atherosclerotic plaque area." (PMID 40076813, 2025). "However, the exact interplay between these elements and the role of NOX5 in c-Src signalling is unknown, especially in the context of human hypertension." (PMID 34320175, 2022). "Therefore, we investigated whether NOX5-derived ROS influences c-Src and its downstream signalling in human hypertension, using VSMCs isolated from small resistance arteries from normotensive (NT) and HT subjects." (PMID 34320175, 2022). "In addition, podocytes express the Ca2+-regulated NOX5 isoform, which could, in some pathological conditions, exacerbate podocyte dysfunction, contributing to albuminuria and hypertension." (PMID 35740870, 2022). "NOX5-dependent hypertension may be such an endotype but apply only to a subset of patients." (PMID 33170835, 2020). "Finally, NOX5 has been shown to be a key player in human hypertension, and a recent paper has revealed that a component of vascular smooth muscle cell dysfunction is an AngII/NOX5/proto-oncogene tyrosine-protein kinase Src signaling network which can alter actin polymerization and cell migration." (PMID 36776559, 2023). "In conclusion, we identify NOX5 as a major source of oxidative stress and aberrant VSMC signalling in human hypertension." (PMID 34320175, 2022). "Together these results suggest that NOX5/c-Src regulates VSMC function by influencing cytoskeletal organization, which in the presence of oxidative stress in hypertension leads to cytoskeletal reorganization and VSMC migration." (PMID 34320175, 2022). "These processes appear to be NOX5- and redox-sensitive because NOX5 siRNA, melittin, SOD, and catalase attenuated responses in hypertension." (PMID 34320175, 2022). "Our findings define NOX5/ROS/c-Src as a novel signalling pathway in human VSMCs and suggest a feedforward loop between NOX/ROS and redox-regulated c-Src, which is amplified in hypertension and which contributes to VSMC dysfunction." (PMID 34320175, 2022). "In the absence of NOX5 specific inhibitors, we tested the possible role of NOX5 in endothelial NO-cGMP signaling dysfunction and hypertension in mice." (PMID 33170835, 2020). "The mechanistic validation of this role of NOX5 in hypertension was performed in a preclinical mouse KI model expressing Nox5, not present in the mouse genome, in the physiological cell type, endothelial cells where NOX5 is important for endothelial migration and angiogenesis." (PMID 33170835, 2020). "As a potential limitation to our study, we did not re-examine in vivo in Nox5 KI mice the efficacy of sepiapterin to reverse NOS uncoupling and hypertension." (PMID 33170835, 2020). "Of note, in other animal models of hypertension—e.g., spontaneously hypertensive (SHR) and Dahl salt-sensitive rats, in which NOX5 is not present—antioxidants can reduce blood pressure." (PMID 33170835, 2020). "Unlike NOX4, NOX5 produces superoxide, which can either uncouple endothelial NOS in hypertension by oxidation of H4Bip in a sepiapterin-reversible manner or scavenge NO to form peroxynitrite, which may also act as a cytotoxic agent or vasodilator." (PMID 33170835, 2020).
diabetic nephropathy (12 papers, 2019 to 2024). "Upregulation of NOX5 in diabetic nephropathy in human podocytes has been associated with filter barrier disruption." (PMID 36829947, 2023). "Regarding NOX5, this enzyme is physiologically expressed in vascular endothelial cells of human blood vessels and may be associated with diabetic nephropathy; mice expressing human Nox5 in vascular smooth muscle cells are, however, normotensive." (PMID 33170835, 2020). "On the other hand, in an in vitro model of diabetic nephropathy, miR-485 suppresses inflammation and proliferation of human mesangial cells by suppressing the expression of NOX5." (PMID 36905456, 2023). "Recently, NOX5 expression was found to be increased in human biopsy samples of patients with diabetic nephropathy as well." (PMID 37760075, 2023). "For instance, NOX5-dependent ROS increased the systolic blood pressure levels in a podocyte-specific NOX5 expression knock-in mouse model or participated in diabetic nephropathy progression." (PMID 34439558, 2021). "A clinical study depicted the presence of NOX5 in the renal vasculature, while another study showed correlation between NOX5 expression in the kidney and tissue injury in diabetic nephropathy." (PMID 32298299, 2020). "Nox5 is expressed in adult human kidneys and is upregulated in chronic kidney disease, including diabetic nephropathy." (PMID 30334629, 2019). "These mice also had podocyte foot process effacement, suggesting a deleterious role of Nox5 in podocyte damage and development of albuminuria in diabetic nephropathy." (PMID 30334629, 2019). "A study showed that the overexpression of miR-485 in human mesangial cells alleviated the high glucose (HG)-induced production of ROS and MDA, upregulated SOD, and attenuated inflammation and proliferation of mesangial cells in an in vitro model of diabetic nephropathy by targeting Nox5." (PMID 38671903, 2024). "Likewise, it has been observed that NOX5 is expressed in renal tubule cells and that in conditions of diabetic nephropathy, its overexpression affects the correct functioning of the renal system." (PMID 36905456, 2023). "Furthermore, an increase in NOX5-derived ROS is essential for the faster progression of diabetic nephropathy." (PMID 37760075, 2023). "Notably, APX-115 treatment also ameliorated diabetic kidney disease in NOX5 pod+ mice." (PMID 37242602, 2023). "In a diabetic kidney disease model, the lack of NOX4 and the expression of NOX5 enhanced albuminuria and renal fibrosis were enhanced, in part via TXNIP activation." (PMID 36358519, 2022).
endothelial dysfunction (11 papers, 2019 to 2025). In vascular diseases, endothelial dysfunction is a systemic pathological state of the endothelium (the inner lining of blood vessels) and can be broadly defined as an imbalance between vasodilating and vasoconstricting substances produced by (or acting on) the endothelium. "In hypertensive patients, endothelial cells have elevated NOX5/ROS levels, which lead to eNOS uncoupling, promoting additional O2•− production and causing endothelial dysfunction." (PMID 39765782, 2024). "Angiotensin II is able to activate complex pathways, including Nox5 activation, ROS production, and inflammatory proteins, that eventually cause a rise in oxidative stress and endothelial dysfunction." (PMID 36262466, 2022). "Our group has recently linked NOX5 overexpression with endothelial dysfunction." (PMID 39456453, 2024). "Moreover, this study explored the expression of VEGF, which was previously associated with endothelial dysfunction and albuminuria, and more recently linked with NOX5 in the context of diabetic retinopathy." (PMID 38671844, 2024). "This NOX5 overexpression model places the potential implications of this oxidase in several processes related to endothelial dysfunction as: (i) cell proliferation and apoptosis, (ii) cell metabolism and mitochondrial dysfunction, and (iii) cell migration." (PMID 36358519, 2022). "Nox1, Nox2 and Nox5 promote endothelial dysfunction, inflammation and apoptosis in the vessel wall through the generation of superoxide." (PMID 34571964, 2021). "Humanized endothelial cell Nox5 KI mice represent the first mechanism-based animal model of human age-related hypertension and endothelial dysfunction." (PMID 33170835, 2020). "Collectively, these data suggest that endothelial NOX5 induces endothelial dysfunction by uncoupling of endothelial NOS leading to impaired endothelium-dependent relaxation of muscular conduit arteries and thus systolic hypertension." (PMID 33170835, 2020). "Of particular interest is the regionally selective effect of NOX5, which was reminiscent of the vascular heterogeneity in age-related endothelial dysfunction." (PMID 33170835, 2020). "Furthermore, PFKFB3 enhanced the activities of NOX1 and NOX5, which are major contributors to endothelial dysfunction." (PMID 40002359, 2025). "In general, O2•− production by plasma membrane NOX1, NOX2, and NOX5 is pro-hypertensive by reducing NO bioavailability and promoting eNOS uncoupling, endothelial dysfunction, inflammation, transactivating epidermal growth factor receptor, cell proliferation/migration and apoptosis." (PMID 39765782, 2024). "Endothelial dysfunction is not only characterized by reduced NO bioavailability and another important fact is the increased expression of NOX1, NOX2 and NOX5, associated with inflammation, and reduced production of vasculature-protective biomolecules, such as the product catalyzed by NOX4." (PMID 36467706, 2022). "NOX1, NOX2 and NOX5 are characterized by their direct involvement in the onset of inflammation, apoptosis and endothelial dysfunction, while NOX4, by contrast, is characterized as an important vasoprotective agent, involved in the suppression of cell death pathways and increased NO bioviability." (PMID 36467706, 2022). "Although it has been described as a proinflammatory, our hypothesis is that NOX5 may favor other molecular mechanisms of endothelial dysfunction." (PMID 36358519, 2022). "In conclusion, NOX5 overexpression may favor endothelial dysfunction and participate in the onset of CVDs such as atherothrombosis or stroke by promoting apoptosis, mitochondrial dysfunction, and cytoskeleton changes." (PMID 36358519, 2022). "Notably, sulodexide prevented hyperglycemia-induced overexpression of NOX4 and NOX5, suggesting that this may be a mechanism that prevents excessive ROS generation and endothelial dysfunction." (PMID 36829947, 2023).
endothelial dysfunction (continued). "Collectively, these results allow us to speculate on a possible role of NOX5 in the composition of the vascular ECM, which could lead to the establishment of endothelial dysfunction and the development of complications in cardiovascular diseases." (PMID 39456453, 2024).
myocardial infarction (10 papers, 2014 to 2023). Gross necrosis of the myocardium, as a result of interruption of the blood supply to the area, as in coronary thrombosis. "For instance, NOX5 is overexpressed in cardiac cells after acute myocardial infarction, and it is progressively overexpressed in the vascular wall including endothelial cells during atheroma plaque formation." (PMID 33572841, 2021). "Nox5 has been recently identified in intramyocardial blood vessels and cardiomyocytes after acute myocardial infarction, as well as coronary artery disease in human and is an important modulator of vascular function." (PMID 24505490, 2014). "However, it has been described that NOX5 expression increased in human intramyocardial blood vessels and cardiomyocytes after myocardial infarction." (PMID 37566320, 2023). "Further work within a conditional endothelial NOX5 knock-in mouse, has identified a role for Nox5 in the response to ischaemia as a result of myocardial infarction, with evidence that Nox5-derived ROS may modulate the COX-2 and PGE2 axis in EC." (PMID 34571964, 2021). "NOX1, NOX2, NOX4, and NOX5 are expressed in the vascular wall and are related to different cardiovascular diseases (CVDs), such as atherosclerosis, hypertension, heart failure, or myocardial infarction (MI)." (PMID 32155782, 2020). "Our study reveals an ability of PKCα to directly interact with Nox5 and regulate its activity which may provide as an important mechanism by which inhibition of PKCα protects against cardiovascular disease, including heart failure, myocardial infarction, and coronary artery diseases." (PMID 24505490, 2014). "Nevertheless, our results showed that endothelial NOX5 overexpression did not alter cardiac function even after myocardial infarction." (PMID 37566320, 2023). "Protein kinase C (PKC) also promotes NOX5 overexpression, regulates the endothelial cyclooxygenase-2 (COX-2)/prostaglandin-2 (PGE2) axis, causes ROS overproduction, and accelerates the progression of myocardial remodeling by activating the post-myocardial infarction (MI) inflammatory response." (PMID 36407440, 2022). "Thus, cardiac mRNA expression of NOX5+/−CRE+/− mice and control CRE+/− mice suffering myocardial infarction was analyzed." (PMID 33572841, 2021).
coronary artery disease (8 papers, 2014 to 2023). "In patients with coronary artery disease, NOX5 expression and activity was found to be elevated in coronary arteries." (PMID 37627585, 2023). "A marked increase in NOX5 protein in isolated coronary arteries from patients with coronary artery disease has been noted." (PMID 34440716, 2021). "Expression of Nox5 protein and mRNA was shown to be markedly increased in coronary arteries from patients with coronary artery disease." (PMID 29375391, 2017). "While the elevated vascular NOX5 expression and activity in patients with coronary artery disease support the idea of a deleterious role in cardiovascular diseases, the reduced body weight gain and adipose tissue mass in humanized NOX5 knock-in mice suggest an additional protective role in obesity." (PMID 37627585, 2023). "In the study, Ca2+-dependent NADPH-driven production of reactive oxygen species in vascular membranes, indicating NOX5 activity, was increased seven-fold in coronary artery disease patients’ specimens, and the activity correlated significantly with NOX5 mRNA levels among subjects." (PMID 34440716, 2021). "In patients with coronary artery disease, expression of Nox5, both at the mRNA and protein levels, was markedly increased compared with those patients without coronary artery disease." (PMID 30334629, 2019). "Nox5 is not present in rodents, and as a result the study of their function in angiogenesis lags behind due to the lack of suitable animal models; however, an increase of Nox5 expression and activity in coronary artery disease and in atherogenesis has been reported." (PMID 28505091, 2017).
prostate carcinoma (8 papers, 2016 to 2024). A carcinoma that arises from epithelial cells of the prostate gland. "The NOX5 dysfunction results in transformation and uncontrolled growth of a variety of cancer cells such as prostate cancer, esophageal adenocarcinoma, hairy cell leukemia, pancreatic cancer and esophageal cancer." (PMID 39850563, 2024). "From these results, it can be said that NOX5 mRNA is widely expressed in prostate cancer cell lines." (PMID 29065504, 2017). "On the other hand, decreased mRNA expression of NOX5 in prostate cancer, as compared to benign tissues, has been reported." (PMID 29065504, 2017). "Actually, NOX5 is held to be the most consistently expressed member of the NOX family in prostate cancer cell lines." (PMID 29065504, 2017). "NOX5 expression plays a role in inducing proliferation and survival in prostate cancer." (PMID 39596205, 2024). "In addition, NOX5 has been also described as a proliferative oxidase in human hepatic stellate cells LX-2, prostate cancer cells, and breast cancer cells." (PMID 36358519, 2022). "Furthermore, SREBP-1 increased reactive oxygen species (ROS) levels via increased NADPH oxidase 5 (Nox5) expression in prostate cancer cells." (PMID 33737530, 2021). "Some studies have shown that NOX1 and its transmembrane subunit P22phox and NOX5 are overexpressed in prostate cancer, and downregulated NOX5 expression can inhibit cell proliferation and tumor growth and induce apoptosis of prostate cancer cells." (PMID 34336107, 2021). "From these facts, NOX5 is thought to stimulate the cell survival of prostate cancer cells." (PMID 29065504, 2017). "Its silencing results in a lower proliferation rate of prostate cancer PC-3 cells and increased apoptosis caused by enhanced activity of caspases 3 and 7, and therefore, NOX5-derived ROS are suggested to be important for the regulation of proliferation and survival of prostate cancer cells." (PMID 28626501, 2017). "Thus, NOX1, NOX2, NOX4, and NOX5 may be potential targets for therapeutic intervention in prostate cancer." (PMID 34336107, 2021). "The opposite result was observed for stem-like holoclones derived from the PC3 human prostate cancer cell line, which showed reduced expression of NOX2, NOX4, and NOX5, and their upregulation significantly lowered cell survival in vitro." (PMID 28626501, 2017). "Lower expression of NOX5 resulted in a decreased level of phosphorylation of c-Jun N-terminal kinase 1/3 (JNK1/3) and a reduced level of PKC-ζ protein, which is known to promote an aggressive phenotype of human prostate cancer cells." (PMID 28626501, 2017). "On the other hand, no significant change in NOX5 mRNA levels was observed upon castration in rats with prostate cancer." (PMID 29065504, 2017). "In addition, studies have reported that various isoforms of NOX are found in prostate cancer cell lines, including NOX4, NOX2, and NOX5, which are absent in normal prostate cell lines." (PMID 34336107, 2021).
Stroke (8 papers, 2012 to 2024). Sudden impairment of blood flow to a part of the brain due to occlusion or rupture of an artery to the brain. "In mice expressing human NOX5 in an endothelial cell‐specific manner, blood pressure was elevated and the risk of stroke increased." (PMID 30801870, 2019). "The same study confirmed substantial Nox5 expression in brain endothelial cells, as well as increased ROS production 24 h after stroke induction in Nox5 knock-in mice, when compared to control wild-type animals." (PMID 36290688, 2022). "In another knock in model, NOX5 expression in endothelial and circulating cells produced higher infarct size and worsened physical stroke outcomes." (PMID 36358519, 2022). "Using humanized Nox5 knock-in mice, it was demonstrated that Nox5 leads to increased stroke volume and BBB permeability, and aggravates motor function 24 h after tMCAO induction." (PMID 36290688, 2022). "In an ischemia-reperfusion mouse model, endothelial NOX5 expression produced a higher infarct size after stroke." (PMID 34439558, 2021). "The biological function of NOX5 is to generate superoxide anion, a known mediator of cerebrovascular damage, following stroke." (PMID 34439558, 2021). "This seemed to be especially important in female mice, suggesting sexual dimorphism for NOX5‐related stroke." (PMID 30801870, 2019). "Experimental models suggest that NOX5 also plays a role in the pathophysiology of stroke." (PMID 30801870, 2019). "Interestingly, NOX5 has been recently related with aging and stroke." (PMID 36358519, 2022). "As NOX5 is not expressed in rats and mice, studies investigating this isoform are scarce, and thus to date no data on the role of NOX5 in stroke are published." (PMID 22625431, 2012). "The NADPH oxidase 5 (NOX5) isoform is absent in rodents, and although little is known about the role it may play in disrupting the BBB, it has recently been implicated in experimental stroke." (PMID 34439558, 2021).